REEP5 (receptor accessory protein 5)
Description:
Plays an essential role in heart function and development by regulating the organization and function of the sarcoplasmic reticulum in cardiomyocytes.
Synonyms: C5orf18; DP1; TB2; D5S346; Yip2e; POB16; YOP1
Tractability: Antibody: UniProt predicts a signal peptide or a membrane-spanning region. PROTAC: ubiquitination databases record sites on it; its protein half-life has been measured.
Gene: Protein-coding gene on chromosome 5 (112,876,385 to 112,922,328, reverse strand). Ensembl gene ENSG00000129625.
Subcellular location: Endoplasmic reticulum membrane; Sarcoplasmic reticulum membrane
Subcellular location (Human Protein Atlas): Endoplasmic reticulum
Gene Ontology:
Molecular function: protein binding
Biological process: endoplasmic reticulum membrane organization; endoplasmic reticulum organization
Cellular component: endoplasmic reticulum; endoplasmic reticulum membrane; endoplasmic reticulum tubular network; sarcoplasmic reticulum membrane
Genetic constraint (gnomAD): Loss-of-function variants: 21 observed, 20.72 expected, observed/expected ratio (o/e) 1.01, 90% interval 0.72 to 1.46. The upper end of that interval is the gene's LOEUF score, 1.46, which puts it in group 6 of 6, group 1 being the genes least tolerant of losing a copy. Missense variants: 197 observed, 189.34 expected, observed/expected ratio (o/e) 1.04, 90% interval 0.93 to 1.17. Synonymous variants: 76 observed, 70.99 expected, observed/expected ratio (o/e) 1.07, 90% interval 0.89 to 1.3.
Homologues: Orthologues: guinea pig REEP5 (97% identical), chimpanzee REEP5 (94% identical), macaque REEP5 (94% identical), mouse Reep5 (94% identical), rat Reep5 (90% identical), pig REEP5 (78% identical), tropical clawed frog reep5 (72% identical), zebrafish reep5 (72% identical), dog REEP5 (64% identical), Caenorhabditis elegans yop-1 (43% identical), Drosophila melanogaster ReepB (42% identical), Drosophila melanogaster CG4960 (40% identical), and 3 more. Paralogues in human: REEP6 (54% identical), REEP4 (26% identical), REEP1 (25% identical), REEP2 (25% identical), REEP3 (24% identical).
Diseases named in the same sentence as REEP5 in open-access papers:
REEP5 is named in the same sentence as 35 diseases in open-access papers, as found by Europe PMC text mining. Sharing a sentence is not in itself a finding about the gene and the disease. The quoted sentences say what the papers report.
colon cancer (2 papers, 2014 to 2020). "Similarly, transfection of REEP5 into RKO colon cancer cells results in growth inhibition and induction of apoptosis, suggesting it functions as a tumour suppressor." (PMID 32357859, 2020).
heart failure (2 papers, 2020). Inability of the heart to pump blood at an adequate rate to meet tissue metabolic requirements. "Further, in vivo CRISPR/Cas9-mediated REEP5 loss-of-function zebrafish mutants showed sensitized cardiac dysfunction to heart failure induction upon short-term verapamil treatment." (PMID 32548572, 2020). "Similarly, pressure overload-induced heart failure via transverse aortic constriction (TAC) led to a downregulation of REEP5 at 2 and 10 days post surgery; however, a moderate increase was seen after 21 days." (PMID 32075961, 2020).
lung carcinoma (2 papers, 2016 to 2023). "The results clearly indicated that REEP5 and REEP6 were required for proper growth and migration of A549 lung cancer cells in vitro and in vivo." (PMID 27966653, 2016). "In A549 lung cancer cells, which endogenously express CXCR1, the depletion of REEP5 and REEP6 significantly reduced growth and invasion by downregulating IL-8-stimulated ERK phosphorylation, actin polymerization and the expression of genes related to metastasis." (PMID 27966653, 2016). "Interestingly, REEP5 and REEP6 activate interleukin-8 (IL-8)/CXC chemokine receptor 1 (CXCR1, a G-protein coupled receptor) signaling to promote tumor cell proliferation/migration, angiogenesis, and macrophages/neutrophils recruitment in the tumor microenvironment in lung cancer." (PMID 37238941, 2023).
myocardial infarction (2 papers, 2020 to 2024). Gross necrosis of the myocardium, as a result of interruption of the blood supply to the area, as in coronary thrombosis. "Myocardial infarction (MI) in the mouse and ischemic cardiomyopathy in the human showed a downregulation of REEP5." (PMID 32075961, 2020).
Obesity (2 papers, 2021 to 2022). Accumulation of substantial excess body fat. "A protein of the same family as REEP5, i.e., REEP6, has been shown to be regulated by thermogenic stimuli in adipose tissue, and furthermore, REEP6 KO mice were defective in cold-induced thermogenesis, showing an obesity-prone phenotype." (PMID 36142750, 2022).
viral infection (2 papers, 2020 to 2023). "Immunoblotting analysis of REEP5 4 weeks post viral infection showed near depleted levels of REEP5 in the AAV9 REEP5 shRNA injected mouse hearts." (PMID 32075961, 2020).
cardiomyopathies (1 paper, 2020). "In fact, such studies may even help determine the therapeutic potential of REEP5 in heart disease as sustained ER stress has emerged as an important contributor to a wide range of prevalent human diseases including cardiomyopathies and congestive heart failure." (PMID 32548572, 2020).
dilated cardiomyopathy (1 paper, 2020). Cardiomyopathy which is characterized by dilation and contractile dysfunction of the left and right ventricles. "A marked decrease in REEP5 mRNA levels was seen in severe dilated cardiomyopathy (DCM) in the mouse and in one human dataset, albeit not significantly." (PMID 32075961, 2020).
fibrosis (1 paper, 2020). the formation of excess fibrous connective tissue in an organ or tissue in a reparative or reactive process. "Additionally, in vivo adeno-associated viral (AAV9)-induced REEP5 depletion in the mouse demonstrated cardiac dysfunction with dilated cardiac chambers, increased cardiac fibrosis, and reduced ejection fraction." (PMID 32548572, 2020).
hypertrophic cardiomyopathy (1 paper, 2020). A condition in which the myocardium is hypertrophied without an obvious cause. "REEP5 protein levels in the context of cardiac disease showed increased REEP5 expression in mouse hypertrophic cardiomyopathy and human idiopathic heart disease, indicating a potential role of REEP5 in the progression and development of heart disease." (PMID 32075961, 2020).
idiopathic cardiomyopathy (1 paper, 2020). A disease of the heart muscle or myocardium proper whose cause is unknown. "In idiopathic cardiomyopathy, REEP5 and myosin heavy chain β (MF20) levels were elevated." (PMID 32075961, 2020).
ischemic cardiomyopathy (1 paper, 2020). Ischemic cardiomyopathy is a cardiomyopathy in which a weakness in the muscle of the heart due to inadequate oxygen delivery to the myocardium with coronary artery disease being the most common cause. "In contrast, REEP5 was downregulated in ischemic cardiomyopathy; in agreement with the GEO data." (PMID 32075961, 2020).
mucinous tumour (1 paper, 2020). "Through the re-sequencing of REEP5 in 23 sporadic AMTs and/or PMP cases, we did not identify any germline REEP5 mutations, despite a shared LoF variant found in our family, and the loss of REEP5 in a case report of a patient with FAP and an appendiceal mucinous tumour." (PMID 32357859, 2020).
Spastic paraplegia (1 paper, 2020). Complete loss of the ability to move the lower limbs accompanied by spasticity of the lower limbs. "Except of REEP5, all these proteins are causative for different forms of spastic paraplegias in humans." (PMID 33329738, 2020).
tumor (7 papers, 2014 to 2025). "In this study, we predicted candidate genes targets of miR-1229, among which PRRG4, REEP5, and PSMB5 were associated with a poor prognosis and highly expressed in tumor tissues." (PMID 33854621, 2021). "REEP5 has been recognized as a binding partner of CXCR1, subsequently triggering the IL-8-CXCR1/2 signaling pathway and facilitating the growth and metastasis of diverse tumor cell types." (PMID 40584831, 2025). "Statistical analysis revealed that tumor growth was remarkably reduced in the mice lacking both REEP5 and REEP6." (PMID 27966653, 2016).
infection (6 papers, 2018 to 2025). The state of being infected such as from the introduction of a foreign agent such as serum, vaccine, antigenic substance or organism. "To measure viral RNA replication, we performed RT-qPCR analysis of SARS-CoV-2 RNA expression in REEP5 KO and WT Calu-3 cells at 0, 6, and 24 hours after infection with SARS-CoV-2." (PMID 37768083, 2023). "Similar to previous reports about virus-induced DMVs, we observed DMVs with an average diameter of 150–350 nm, which were often clustered together in both parental and REEP5 KO Caul-3 cells at 24 hours after infection." (PMID 37768083, 2023). "As the TRAM1 KO Calu-3 cells stopped dividing after infection, probably due to virus-induced cellular senescence, we validated REEP5 KO Calu-3 cells with immunoblot." (PMID 37768083, 2023). "Importantly, we confirmed the endogenous binding between viral NSP3 and REEP5/TRAM1 complex in Calu-3 cells after infection with SARS-CoV-2." (PMID 37768083, 2023). "To understand the role of REEP5 in ER morphology and SARS-CoV-2-induced DMVs, we infected parental and REEP5 KO Calu-3 cells with SARS-CoV-2 and compared their morphology at 0 and 24 hours after infection using electron microscopy." (PMID 37768083, 2023).
cancer (5 papers, 2016 to 2025). A tumor composed of atypical neoplastic, often pleomorphic cells that invade other tissues. "REEP5 is associated with pathways like PI3K-Akt signaling and oxidative phosphorylation, crucial for cancer growth and survival." (PMID 40722386, 2025). "Genes such as PYGM, BMF, MBNL3, DENND6A, REEP5, KLF6 and ITM2C are potentially regulated by circYPEL2 and involved in cancer-specific pathways, which are needed to be validated in further studies." (PMID 35052380, 2021). "Gene expression analysis revealed that REEP5 was overexpressed in some advanced cancer tissue, whereas its roles in cancer progression were not clarified yet16." (PMID 27966653, 2016).
heart disease (2 papers, 2020). "From our depletion and knockout studies, it is evident that REEP5 is important in the normal functioning of the heart and potentially has a role in cardiac disease." (PMID 32548572, 2020). "REEP5 levels changed dramatically with several cardiac diseases." (PMID 32075961, 2020).
cardiovascular diseases (1 paper, 2020). "We next queried publicly available GEO RNA-seq datasets containing data for human and mouse cardiovascular diseases to determine changes in REEP5 expression." (PMID 32075961, 2020).
REEP5 also shares sentences with these, for which no sentence is quoted: tuberculosis (5 papers); COVID-19 (2); hereditary spastic paraplegia (2); autosomal dominant spastic paraplegia (1); autosomal dominant spastic paraplegia 3A (1); autosomal dominant spastic paraplegia 4 (1); Cerebral ischemia (1); cerebral malaria (1); colorectal cancer (1); Familial adenomatous polyposis (1); Insulin resistance (1); lipid metabolism disorders (1); muscular dystrophy (1); prostate carcinoma (1); rheumatoid arthritis (1); Troyer syndrome (1).